BRCA1 (BRCA1 DNA repair associated)
Diseases named in the same sentence as BRCA1 in open-access papers (continued):
Sharing a sentence is not in itself a finding about the gene and the disease.
pancreatic cancer (continued). "For example, cisplatin/gemcitabine doublet demonstrated a remarkable efficacy in BRCA1/BRCA2/PALB2-driven hereditary pancreatic cancer." (PMID 34454564, 2021). "A phase 2 study (NCT02042378) focused on the efficacy and safety of rucaparib in BRCA1/2 mutant patients with measurable locally advanced/metastatic pancreatic cancer." (PMID 32122376, 2020). "Three studies have published significantly improved survival and responses to platinum-based chemotherapy for BRCA-positive pancreatic cancers; therefore, gemcitabine plus cisplatin is recommended by the NCCN for UPC with BRCA1/2 or PABL2 mutation." (PMID 33704188, 2020). "The results of the phase III Pancreas Cancer Olaparib Ongoing (POLO) trial, which showed great promise for enrolled patients with metastatic pancreatic cancer with mutation in BRCA1 or BRCA2, who were previously treated with platinum-based chemotherapy." (PMID 32635552, 2020). "Estimates vary, but around 5–15% of all patients with pancreatic cancer have a detectable pathogenic DDR-related gene variant, and around 5% have a BRCA1/2 variant specifically." (PMID 32793315, 2020). "Breast cancer type 1 susceptibility protein (BRCA1) and Breast cancer type 2 susceptibility protein (BRCA2) mutations increase an individual’s risk of several cancer types, including pancreatic cancer." (PMID 33198737, 2020). "Mutations in BRCA1/2 and in Partner and Localizer of BRCA2 (PALB2) genes are reported in approximately 5% to 9% of pancreatic cancer patients." (PMID 32366019, 2020). "Female BRCA1/2 mutation carriers are at significantly increased risk for BC, OVC, and pancreatic cancer." (PMID 33643918, 2020). "Tissue-specific Brca1 knockout or mutations, in combination with other transgene or gene knockout, have also been generated for studying BRCA1’s role in the development of breast, ovarian, and pancreatic cancers." (PMID 32257107, 2020). "The benefits of PARP inhibitor-mediated synthetic lethality for those with germline BRCA1 or BRCA2 mutations are now undeniable and highlights the importance of germline testing for all patients with pancreatic cancer." (PMID 32030362, 2019). "Overall, pathogenic BRCA1 and BRCA2 germline variants were observed in patients with expected malignancies such as breast, ovarian, prostate and pancreatic cancer, a large proportion of which showed loss of the wild-type allele in the tumor sample." (PMID 31263571, 2019). "A number of studies have shown that pedigrees with germline mutations in ATM, BRCA1, and BRCA2 also have an increased lifetime risk of pancreatic cancer in familial pancreatic cancer (FPC) kindreds." (PMID 31480737, 2019). "As PALB2 mutations also have been observed in families with breast, ovarian and pancreatic cancer like BRCA1/2, the PALB2 gene has also been recognized as a tumor susceptibility gene." (PMID 31877165, 2019). "Like BRCA1 (FANCS) and BRCA2 (FANCD1), monoallelic mutations in PALB2 confer familial susceptibility to breast, ovarian and pancreatic cancer, while biallelic PALB2 lesions cause Fanconi anemia (FA) subtype N (FANCN)." (PMID 31877165, 2019). "The BRCA mutations, detected in our families with a history of pancreatic cancer, were more frequently located in the longest exon of each gene, EXON10 of the BRCA1 gene and in the EXON11 of the BRCA2 gene." (PMID 30736435, 2019). "In contrast to KPC animals (n = 28, T50 = 24.6 weeks), Palb2-KPC, Brca1-KPC or Brca2-KPC respectively developed PDAC with a much shorter pancreatic tumor-free median survival of 10.1, 11.9 and 13.7 weeks, respectively." (PMID 31877165, 2019). "In particular, 6 families (one of which BRCA1 positive) showed three pancreatic cancer cases, and 31 families (4 of which BRCA1 positive and 2 of which BRCA2 positive) showed two pancreatic cancer cases." (PMID 30736435, 2019). "Among pancreatic tumors of patients with PALB2, as for BRCA1/2 mutation carriers, LOH has been reported." (PMID 31877165, 2019).
pancreatic cancer (continued). "It was found that the family with BRCA1 mutant had pancreatic cancer, gastric cancer, cervical cancer and esophageal cancer, while the family with BRCA2 mutant had lung cancer, rectal cancer and close relatives of retroperitoneal tumor." (PMID 31775908, 2019). "In familial pancreatic cancer, BRCA2 is mutated in about 5% to 10% of cases and BRCA1 in approximately 1%." (PMID 31540286, 2019). "There are no clear guidelines regarding screening of digestive cancers in BRCA2 carriers and even for pancreatic cancer screening (part of both the BRCA1 and BRCA2 phenotype) the recommendation is to include those carriers in prospective studies." (PMID 29456621, 2018). "Of more interest are the DDR-related pancreas cancers, which include the genes in the homologous recombination (HR)-pathway (e.g., BRCA1/2)." (PMID 30186770, 2018). "Family studies have demonstrated that both BRCA1 and BRCA2 mutation carriers have an increased risk of developing pancreatic cancer." (PMID 29777302, 2018). "BRCA1 and BRCA2 are the most common of the known genetic mutations involved in familial pancreatic cancer." (PMID 29777302, 2018). "In one recent cohort study of over 300 patients with pancreatic cancer, pathologic germline mutations in BRCA2 were identified in 3.3%, BRCA1 mutations in 1.2%, and PALB2 in 0%." (PMID 28454122, 2017). "Three tag missense polymorphisms (rs1799966 on BRCA1; rs766173 and rs144848 on BRCA2) were genotyped in 603 pancreatic cancer patients in a Chinese population." (PMID 28415599, 2017). "Our study shows a high incidence of abnormal pancreatic imaging findings in patients with BRCA1/BRCA2 genetic mutations, including pancreatic atrophy, cysts, ductal dilation, and pancreatic cancer." (PMID 27069714, 2016). "Carriers of BRCA1 and BRCA2 mutations genes are at an increased risk for cancer at body sites other than breast, such as prostate, stomach, pancreatic cancers and melanoma." (PMID 27377827, 2016). "We have recently shown that germline mutations of BRCA1 and BRCA2 sensitize pancreatic cancers to treatment with cisplatin and gemcitabine." (PMID 28033382, 2016). "It has been known that patients of hereditary breast and ovarian cancer syndrome (HBOC), caused by a germline mutation in BRCA1 or BRCA2, have an increased risk for breast, ovarian, prostate and pancreatic cancers." (PMID 26766567, 2016). "Results showed that 11 % of the 219 BRCA1 positive families had at least one relative with pancreatic cancer and 2.7 % had more than one relative with pancreatic cancer." (PMID 26236408, 2015). "Some tumors with inactivating mutations of BRCA1 or BRCA2, such as some breast and pancreatic cancers, have substantial numbers of larger deletions (up to 50 bp) with overlapping microhomology at breakpoint junctions." (PMID 26083936, 2015). "Through analysis of the literature it was found that both BRCA1 and BRCA2 mutations are associated with the incidence of pancreatic cancer and that BRCA2 mutation poses an increased risk for developing pancreatic cancer." (PMID 26236408, 2015). "Targeting defects in the DNA repair machinery of neoplastic cells, for example, those due to inactivating BRCA1 and/or BRCA2 mutations, has been used for developing new therapies in certain types of breast, ovarian and pancreatic cancers." (PMID 26511885, 2015).
pancreatic cancer (continued). "Various forms of CEA, integrins, BRCA1, and tumor-associated glycoprotein-17 (TAG-17) are overexpressed on pancreatic tumor cells while c-MET, EpCAM, and CXCR-4 are also used as pancreatic cancer stem cell markers." (PMID 25157372, 2014). "Considering these two PALB2 variants as causal mutations, the prevalence of PALB2 mutation in our BRCA1/BRCA2 breast and pancreatic cancer series is 1.5% (2/132)." (PMID 23935836, 2013). "Hypomethylation of satellite II involving the pericentromere of chromosome-1 has been reported in BRCA1, pancreatic cancer, and other epithelial cancers." (PMID 23429197, 2013). "Recent trials and clinical observations have confirmed the efficacy of platinating agents and PARP inhibitors in BRCA1/2-driven breast, ovarian and pancreatic carcinomas." (PMID 23548133, 2013). "In the same line, 60% of pancreatic carcinomas were recently found to be hypermethylated at the BRCA1 gene and the number of methylated genes significantly correlated to DNMT1 protein overexpression." (PMID 17047656, 2006). "Moreover, the presence of BRCA1 and BRCA2 mutations in PCa patients increased the risk of developing other tumors, such as male breast cancer, cancer of the pancreas, and melanoma, as compared with the incidence in the general population." (PMID 41590381, 2026). "LAE119 has more efficient anti-proliferative effects on BRCA1/2-mutated breast, colon, and pancreatic cancer cell lines than does AZD5305 and exhibits substantial tumor inhibition with reduced toxicity in BRCA-mutated breast and pancreatic cancer CDX models." (PMID 40521389, 2025). "Upstream regulatory mutations in BRCA1 and PALB2 may further influence miR-184’s apoptotic effects in breast and pancreatic cancers, illustrating how its function depends on the dominance of specific pathways or ceRNA dynamics within a given tumour context." (PMID 41379397, 2025). "Finally in pancreatic cancer, trials with niraparib and rucaparib in patients with HRD-mutations other than BRCA1/2, including BRIP1, are ongoing." (PMID 40988318, 2025). "BRCA gene mutations have been shown in two meta-analyses to be associated with a high increased risk of pancreatic cancer (RR 2.65; 95% CI 1.43–4.91), with an indication this risk is higher in BRCA2 (RR 5.12; 95% CI 3.17–8.27) than in BRCA1 (RR 1.71; 95% CI 1.16–2.52) mutations." (PMID 40584837, 2025). "Genetic syndromes, such as those resulting from inherited mutations in genes like STK11, BRCA1, BRCA2, PALB2, CDKN2A, and DNA repair genes, notably elevate the risk of pancreatic cancer, particularly in individuals with a family history of pancreatic cancer among first-degree relatives." (PMID 39949443, 2025). "BRCA1 and BRCA2 are key tumor suppressor genes involved in DNA repair, and their mutations significantly increase the risk of breast, ovarian, prostate, and pancreatic cancers." (PMID 40718262, 2025). "In the future, NGS will have a greater impact on CDM, as targeted treatment options for CCA and pancreatic carcinoma expand, including US Food and Drug Administration-approved options for mutations in theFGFRpathway,IDH1,ERBB2,BRCA1/2, and microsatellite-instable tumors." (PMID 40932825, 2025). "While inhibitors of PARP have been approved for BRCA-mutated cancers, exploiting synthetic lethality in DNA repair pathways, only 5-10% of pancreatic cancer patients possess BRCA1 or BRCA2 mutations, limiting the applicability of PARP inhibitors in pancreatic cancer treatment." (PMID 39528473, 2024). "Many studies are needed to establish whether BRCA1/2 is epigenetically affected in pancreatic cancer and other tumor types." (PMID 38577595, 2024).
pancreatic cancer (continued). "Thus, to explore the novel mechanisms of resistance to PARP inhibitors, we constructed BRCA1 KO pancreatic cancer cells (C1 cells) and then derived an olaparib-resistant clone (C1/OLA cells) from these cells." (PMID 38625917, 2024). "Still, the most pronounced responses were observed either in patients with already approved organ-specific drug indications (e.g., olaparib in BRCA1/2-driven pancreatic cancer), or in subjects with overtly actionable lesions (ALK fusions, BRAF V600E mutations, microsatellite instability, etc.)." (PMID 38612902, 2024). "Olaparib has been approved as maintenance therapy for patients with BRCA1/2-mutated pancreatic cancer whose disease has not progressed on first-line platinum-based chemotherapy regimens." (PMID 38625917, 2024). "There were 14 pancreatic cancer patients with germline P/LP variants, including 6 with BRCA1/2 variants and 8 with non-BRCA variants." (PMID 38355628, 2024). "However, PARP inhibitors confer little clinical benefit to most pancreatic cancer patients with wild-type BRCA1/2." (PMID 38433576, 2024). "Our present results suggested that repression of KLF5 promoted olaparib-induced DNA damage in pancreatic cancer cells and increased olaparib sensitivity by suppressing the transcription of BRCA1, which could be reversed by upregulation of BRCA1." (PMID 38433576, 2024). "The role of PARP inhibitors in GI cancers is currently limited to a small subset of pancreatic cancers with germline BRCA1 mutations and no progression 16 weeks post platinum." (PMID 39640282, 2024). "A larger cohort of patients is required to further explore the potential of these findings as well as to investigate whether BRCA1/2 methylation in plasma could serve as a potential prognostic biomarker in pancreatic cancer." (PMID 38577595, 2024). "Mutation in BRCA1 and BRCA2 are associated with an increased risk of pancreatic cancer." (PMID 39575418, 2024). "The American Society of Gastrointestinal Endoscopy (ASGE) has similar recommendations for patients with BRCA1, BRCA1, and PALB2 mutations to begin screening for pancreatic cancer at the age of 50 years or 10 years younger than the youngest relative with pancreatic cancer." (PMID 39200847, 2024). "The presence of BRCA1/2 mutations demonstrates a strong correlation with improved overall survival (OS) compared to non-carrier familial pancreatic cancer (FPC) patients." (PMID 38809921, 2024). "Inclusion criteria comprised observational cohort or diagnostic studies related to the role of BRCA1/2 mutation in correlation to familial pancreatic cancer (FPC), while article reviews, narrative reviews, and non-relevant content were excluded." (PMID 38809921, 2024). "Within this corpus of literature, three studies scrutinized the prognosis of familial pancreatic cancer (FPC) individuals in comparison to patients without BRCA1/2 mutations." (PMID 38809921, 2024). "However, most pancreatic cancer patients carry wild-type BRCA1/2 with resistance to PARP inhibitors." (PMID 37415733, 2023). "It is clinically important to note that a minority of pancreatic cancer patients with germline mutations in BRCA1/BRCA2 and other DDR genes have no family history of cancers." (PMID 36975505, 2023). "As expected, BRCA1/2 variants comprised the majority of the tumor/germline variants in patients with stage III/IV breast, ovarian and pancreatic cancers; however, we also detected tumor/germline BRCA2 variants in atypical cancers such as colorectal, esophagogastric, NSCLC, and sarcoma." (PMID 36261688, 2023). "The American Society for Gastrointestinal Endoscopy recommends screening individuals with an increased risk of pancreatic cancer due to genetic susceptibility, including BRCA2 and BRCA1 gene mutations, using imaging methods—EUS, MRI, or a combination of both methods." (PMID 37509296, 2023).
pancreatic cancer (continued). "Indeed, Pancreas Cancer Olaparib Ongoing (POLO) clinical trial has found that Poly ADP-ribose Polymerase inhibitor (PARPi) showed significant benefit in BRCA1/2 mutant PDAC patients." (PMID 37735513, 2023). "Thus, our study provides a novel combination strategy to optimize PARP inhibitor treatment in BRCA1/2 wild-type pancreatic cancers." (PMID 37415733, 2023). "Although pancreatic cancer risks were not shown to be significantly elevated in female relatives of BRCA1 or BRCA2 carriers, a trend toward risk for pancreatic cancer was still observed for female relatives of BRCA2 carriers (RR 2.54, 95% CI 1.02-6.30; P = 0.055)." (PMID 36861435, 2023). "SBS3 is very common in breast, ovarian, and pancreatic cancer with mutations in BRCA1/2 genes; however, it is also present to a smaller extent in other cancer types with no mutations in BRCA1/2 or other genes involved in double-strand break repair." (PMID 37568604, 2023). "In the past decades, studies have found that these unique vulnerabilities inherent in BRCA1/2 mutant cancers (e.g., breast, ovarian, and pancreatic cancers) could be utilized to induce synthetic lethality." (PMID 37735513, 2023). "Currently, the NCCN guidelines for pancreatic cancer have no guidance for individualized chemotherapy, save for a recommendation that patients with germline BRCA1/2 gene mutations choose platinum chemotherapy." (PMID 35664782, 2022). "BRCA1 and BRCA2 PVs can be found in up to nearly 5% of the primary tumors of pancreatic cancer, with the highest frequencies in cohorts enriched for high-risk pancreatic cancer cohorts enriched for familiar cases." (PMID 35563100, 2022). "Over many recent years, multiple investigations had identified that reversions of BRCA1/2 at the genetic level are a cause of PARP inhibitor resistance during ovarian, prostate, breast, and pancreatic cancers." (PMID 35873570, 2022). "In pancreatic cancer, BRCA1 and BRCA2 have a prevalence of 1.7 and 4.5%, respectively." (PMID 34979999, 2022). "In addition, 6-OH DOPA selectively halted proliferation of BRCA1/2 deficient TNBC cells, pancreatic cancer cells and patient-derived AML and CML cells." (PMID 35463312, 2022). "Somatic mutations of BRCA1, BRCA2 and PALB2 are ~14% in pancreatic cancer." (PMID 35328658, 2022). "By panel testing, pancreatic cancer occurs in 0–3% for BRCA1 and 1–6% for BRCA2." (PMID 35454911, 2022). "BRCA1 and BRCA2 genes are part of the homologous DNA repair pathway (HR), and the mutations in these genes are powerful contributors to the development of several cancers, including breast, prostate, ovarian, and pancreatic cancers." (PMID 36556296, 2022). "Our results suggest that individualized selection of chemotherapy combined with sequential immunotherapy according to BRCA1 mRNA expression level in unresectable pancreatic cancer could control the disease and have controllable adverse reactions." (PMID 36387089, 2022). "Since BRCA1/BRCA2 are frequently mutated in PanNETs and are significant predictors of survival outcome in pancreatic cancer patients, we analyzed if BRCA1/2 CNVs could impact the PFS in PanNETs patients." (PMID 36140756, 2022). "Frequency of these mutations in GI tumors are still being elucidated but appear at a wide range dependent on the mutation and GI tumor (i.e., BRCA1 pancreatic cancer = 1.3–1.4%; BRCA2 pancreatic cancer = ~3%; BRCA1 biliary tract cancers = 1%; BRCA2 biliary tract cancers = 2%; etc.)." (PMID 36230726, 2022). "Results of this retrospective study suggested that BRCA1 gene expression level may become a new biomarker for guiding chemotherapy options in patients with unresectable pancreatic cancer." (PMID 36387089, 2022). "Mutation in BRCA1 does not substantially increase the risk of developing pancreatic cancer, but BRCA2 mutations are the most common genetic risk factor for pancreatic cancer with a relative risk of 3.5." (PMID 36500723, 2022).